ITGA2 (integrin subunit alpha 2)
Diseases named in the same sentence as ITGA2 in open-access papers (continued):
Sharing a sentence is not in itself a finding about the gene and the disease.
cervical cancer (5 papers, 2016 to 2025). A primary or metastatic malignant neoplasm involving the cervix. "To investigate the role of ITGA2 in CCa, we modulated ITGA2 expression in SiHa cells, a well-established HPV16-positive cervical cancer cell line that is consistent with CCa tissues we sequenced." (PMID 39634132, 2025). "Transwell migration and invasion assays showed that reducing ITGA2 and ITGA3 expression significantly decreased the migration and invasion of cervical cancer cells." (PMID 38702644, 2024). "MUC1 was overexpressed in CSCC, activating the phosphorylation of ERK, which enhanced the expression of ITGA2 and ITGA3, thereby promoting the malignant progression of cervical cancer cells." (PMID 38702644, 2024). "We treated cervical cancer cells with a new inhibitor of ERK (MK-8353) and found that the expression of ITGA2 and ITGA3 was significantly reduced." (PMID 38702644, 2024). "Further knockdown of ITGA2 and ITGA3 significantly inhibited the tumorigenesis of cervical cancer cells." (PMID 38702644, 2024). "In the present study, we found that the mRNA level of ITGA2 and ITGA3 were increased in cervical cancer patients via the TCGA database." (PMID 38702644, 2024). "MUC1 could upregulate ITGA2 and ITGA3 expression via ERK phosphorylation, promoting the proliferation and metastasis of cervical cancer cells." (PMID 38702644, 2024).
lymph node metastasis (5 papers, 2015 to 2023). "The results revealed that histological grade, TNM stage, lymph node metastasis, local invasion, and the expression of ITGA2, CD4, and CD8 in tumor tissues were all associated with patient prognosis." (PMID 37881431, 2023). "The study findings indicate that the levels of ITGA2, CD4, and CD8 in tumor tissues are significantly associated with histological grade, TNM stage, lymph node metastasis, and local invasion (P < 0.05)." (PMID 37881431, 2023). "In our analysis in PTC, ITGA2 is positively associated with stage III, lymph node metastasis, minimal extrathyroidal extension, and intermediate-risk tumors." (PMID 34208249, 2021). "Our data showed that ITGA2 protein level was positively associated with lymph node metastasis (P = 0.045), but was not related to TNM stage, histological grade, ER, PR, Her2, Ki-67 status, or age." (PMID 26258411, 2015). "However, our results demonstrated that ITGA2 protein level is markedly increased in lymph node metastases." (PMID 26258411, 2015). "Notably, the expression of ITGA2 at a high Gleason score was relatively high in lymph node metastasis and in relapsed versus non-relapsed tumors." (PMID 32824235, 2020).
arterial hypertension (4 papers, 2016 to 2025). "ITGA2 is reported to be associated with hypertension in a Japanese population." (PMID 27980649, 2016). "Aim of the study: To study the distribution of polymorphic variants of integrin ITGA2 (C807T), ITGB3 (T1565C) and the association of genotypes with platelet characteristics in individuals with arterial hypertension in Azerbaijan." (PMID 41346645, 2025). "This study investigates the association of ITGA2 (C807T) and ITGB3 (T1565C) gene polymorphisms with platelet characteristics in Azerbaijani patients with arterial hypertension (AH), focusing on potential thrombotic risk." (PMID 41346645, 2025). "In the arterial hypertension (AH) subgroup, a positive correlation was found between the ITGA2 gene T allele with the MPV indicator (Rho = 0,467; p = 0,011), and between ITGA2 altered genotypes, and MPV (Rho = 0,434; p = 0,019), as well as ITGA2 altered genotypes (Rho = 0,391; p = 0,036)." (PMID 41346645, 2025).
Arterial thrombosis (4 papers, 2016 to 2022). The formation of a blood clot inside an artery. "SNPs in ITGA2 and ITGB3 increase the risk of arterial thrombosis by affecting platelet receptors." (PMID 36362614, 2022).
breast tumor (4 papers, 2017 to 2024). "A recent study on ITGA2 showed that the miR-373 represses the expression of ITGA2 and stimulates the migration of breast tumor cells." (PMID 28587194, 2017).
nasopharyngeal carcinoma (4 papers, 2017 to 2024). A carcinoma arising from the nasopharyngeal epithelium. "The polymorphisms of ITGA2 gene was related to the poor survival of nasopharyngeal carcinoma." (PMID 30428899, 2018). "VIRMA enhances mRNA stability and transactivates integrin subunit alpha (ITGA2), promoting nasopharyngeal carcinoma progression." (PMID 39006762, 2024). "We conducted a 1 to N case-control study involving 300 nasopharyngeal carcinoma (NPC) cases and 533 controls matched by age, gender and ethnicity to investigate the effect of hOGG1 Ser326Cys, ITGA2 C807T and XPD Lys751Gln polymorphisms on NPC risk." (PMID 29121049, 2017).
neuroblastoma (4 papers, 2017 to 2024). Neuroblastoma (NB) is the most common solid, extracranial childhood tumor. "We first assessed expression of the Itga2 gene, which encodes the CD49b antigen, in mouse 3T3 Swiss fibroblast cells, as well as in the murine neuroblastoma cell line Neuro-2a (N2a), which lacks Mycn amplification." (PMID 38095019, 2023). "We investigated whether the cell-surface marker CD49b (integrin α2, encoded by Itga2 in mice), which marks proliferative neural crest progenitor cells, distinguishes neuroblastoma populations with distinct gene expression programs." (PMID 38095019, 2023). "Using mouse and human neuroblastoma cell lines lacking MYCN amplification, we show that the antigen CD49b (also known as ITGA2) distinguishes these subpopulations." (PMID 38095019, 2023).
small cell lung carcinoma (4 papers, 2018 to 2022). Small cell lung cancer (SCLC) is a highly aggressive malignant neoplasm, accounting for 10-15% of lung cancer cases, characterized byrapid growth, and early metastasis. "DEGs found to be associated with the small cell lung cancer pathway (ITGA2) and other cancer pathways (MMP1), based on KEGG analysis, were highly expressed in KRAS-mutant AAH." (PMID 34943992, 2021). "Additionally, ITGA2 and FN1 were associated with GO terms and pathways related to extracellular matrix (ECM) organization and cancer (hsa05222: small cell lung cancer, hsa04512: ECM-receptor interaction, hsa05200: pathways in cancer)." (PMID 30414611, 2018).
thyroid cancer (4 papers, 2020 to 2022). "HSP90B1 can also affect the progression of thyroid cancer by regulating the expression and sub-localization of its client protein ITGA2." (PMID 36291587, 2022). "Among the top 30 hub genes obtained in PPI network, the expression levels of FN1, NMU, CHRDL1, GNAI1, ITGA2, GNA14 and AVPR1A were associated with the prognosis of thyroid cancer." (PMID 32337286, 2020). "The α2β1 complex is the one with higher upregulation in thyroid carcinomas (up to 9-fold for ITGA2 vs. 2.5-fold for ITGA3 and ITGAV), although it is not the most abundant integrin expressed." (PMID 34208249, 2021). "The Human Protein Atlas (HPA)-based Immunohistochemistry (IHC) database showed that FN1, NMU, and ITGA2 were upregulated in thyroid cancer tissues compared with normal tissues, while CHRDL1, GNAI1 and GNA14 were downregulated in thyroid cancer tissues." (PMID 32337286, 2020). "Hence, we derived seven key genes related to the prognosis of thyroid cancer: FN1, NMU, CHRDL1, GNAI1, ITGA2, GNA14, AVPR1A." (PMID 32337286, 2020).
acute myeloid leukemia (3 papers, 2017 to 2025). Acute myeloid leukemia (AML) is a group of neoplasms arising from precursor cells committed to the myeloid cell-line differentiation. "ITGA2 gene expression was found higher in 134 de novo acute myeloid leukemia (AML) patients in comparison with the 33 controls." (PMID 41008552, 2025). "As for acute myeloid leukaemia (AML), overexpression of ITGA2 was connected with lower 5‐year survival." (PMID 32557953, 2020).
aortic aneurysm (3 papers, 2020 to 2022). A ruptured aneurysm located in the wall of the proximal portion of the descending aorta proceeding from the arch of the aorta. "Previous study demonstrated ITGA2-deficient mice overexpressed transforming the growth factor TGFβ, which was known to be highly associated with aortic aneurysm and IA." (PMID 32450902, 2020). "Moreover, ITGA2 was found to be abnormally expressed in a mouse model of aortic aneurysms, another severe aortic disease." (PMID 35096998, 2021).
Autoimmunity (3 papers, 2019 to 2025). The occurrence of an immune reaction against the organism's own cells or tissues. "Cells within the CD4_Stim2.Th17.1 cluster expressed genes associated with regulatory function (IL10, ITGA2), whereas cells within the CD4_Stim2.Th17.2 cluster expressed proinflammatory effectors (IFNG, IL23R, PRF1), described to be produced by pathogenic Th17 cells in autoimmunity." (PMID 35192548, 2022).
carotid atherosclerosis (3 papers, 2023 to 2024). A thickening and loss of elasticity of the walls of carotid arteries that occur with formation of atherosclerotic plaques. "The high-risk interactive genotypes among IL1A rs1609682, ITGA2 rs1991013, and HABP2 rs7923349 significantly increased the risk of carotid atherosclerosis." (PMID 37292135, 2023). "There was a significant gene–gene interaction observed in IL1A rs1609682, ITGA2 rs1991013, and HABP2 rs7923349, the high-risk interactive genotypes in the three variants served as independent risk factors of carotid atherosclerosis." (PMID 37292135, 2023). "Furthermore, multivariate logistic regression was employed to evaluate the risk of carotid atherosclerosis conferred by the high-risk interactive genotypes among IL1A rs1609682, HABP2 rs7923349, and ITGA2 rs1991013." (PMID 37292135, 2023). "The results exhibited that the high-risk interactive genotypes in IL1A rs1609682, ITGA2 rs1991013, and HABP2 rs7923349 were independently associated with a higher risk for carotid atherosclerosis after adjusting covariates (OR, 2.08, 95% CI: 1.257–5.980, P < 0.001)." (PMID 37292135, 2023). "In addition, although we found that the high-risk interactions among IL1A rs1609682, ITGA2 rs1991013 and HABP2 rs7923349 increased the risk of carotid atherosclerosis, the detailed molecular mechanisms were not investigated." (PMID 37292135, 2023).
diabetic retinopathy (3 papers, 2008 to 2024). "In control subjects, the frequencies of ITGA2 BglII polymorphisms for genotypes -/-, -/+, and +/+ were, respectively, 46.9, 45.1, and 8.0 matching prior reports in diabetic retinopathy and in diabetic patients." (PMID 35936750, 2022).
esophageal cancer (3 papers, 2023 to 2024). A primary or metastatic malignant neoplasm involving the esophagus. "Genomic loss or deletion of ITGA1/ITGA2 locus was found to be highly frequent in PCa cases and equally prevalent in ovarian and esophageal cancers, suggesting that the tumor suppressor functions of α1‐ and α2‐integrins might not be limited to PCa." (PMID 38169150, 2024). "In esophageal malignant tumors, ITGA2 overexpression promotes tumor growth, invasion, and migration." (PMID 37881431, 2023). "Previous studies showed that ITGA2 overexpression increased cell proliferation and reduced apoptosis by upregulating phospho-AKT (pAKT) in ovarian and esophageal cancer." (PMID 36765586, 2023).
intrahepatic cholangiocarcinoma (3 papers, 2022 to 2025). A carcinoma that arises from the intrahepatic bile duct epithelium in any site of the intrahepatic biliary tree. "Moreover, another study showed that ITGA2 is upregulated in intrahepatic cholangiocarcinoma (iCCA) and promotes tumor growth by mediating strong interactions with collagen type I in the extracellular matrix, suggesting the collagen type I–integrin α2 axis as a potential therapeutic target for iCCA." (PMID 41008552, 2025).
leukemia (3 papers, 2024 to 2025). A malignant (clonal) hematologic disorder, involving hematopoietic stem cells and characterized by the presence of primitive or atypical myeloid or lymphoid cells in the bone marrow and the blood. "Leukemia patients with overexpression of ITGA2, COL6A1, cyclin D1, PKN1, PDGFRA, or F2R predict or have trends toward worse prognosis." (PMID 41203598, 2025). "Leukemia patients with overexpression of ITGA2, COL6A1, cyclin D1, PKN1, PDGFRA or F2R predicts or has trends toward worse prognosis." (PMID 39764125, 2024). "The results showed that ITGA2 expression significantly varied across these leukemia types." (PMID 41008552, 2025). "In addition, data represented that ITGA2 expression changes across leukemia types." (PMID 41008552, 2025).
malaria (3 papers, 2016 to 2020). Malaria is a serious and sometimes fatal disease caused by a parasite that commonly infects a certain type of mosquito which feeds on humans. "Expressions of Itga1 and Itga2 induced in the liver in response to infection with blood-stage malaria and vaccination take similar courses as those detected by microarrays." (PMID 33202767, 2020). "In particular, the qRT-PCR data show that Itga1 expression in response to malaria reveals a maximum in non-vaccinated mice on day 4 p.i., while the malaria-induced Itga2 expression is largely impaired until day 4 p.i., before it continuously increases, reaching maximum on day 11 p.i." (PMID 33202767, 2020).
pancreatic adenocarcinoma (3 papers, 2012 to 2022). "We used Gene Expression Omnibus (GEO) database and identified six genes (COL1A2, ITGA2, ITGB6, LAMA3, LAMB3, and LAMC2) that could affect the survival rate of pancreatic adenocarcinoma patients." (PMID 35899199, 2022). "After analyzing the mRNA expression level of ITGA2 in several cancers and non-tumor tissues using the GEPIA web tool, we found that the mRNA expression level of ITGA2 was significantly up-regulated in pancreatic adenocarcinoma (PAAD) and stomach adenocarcinoma (STAD) a." (PMID 31818309, 2019).
prostate tumor (3 papers, 2015 to 2024). "We assessed whether the genomic alterations of ITGA1/ITGA2 display any clinical impacts on PCa, and thus investigated potential correlation between ITGA1/ITGA2 copy number loss and their expression levels in human prostate tumors." (PMID 38169150, 2024). "The results indicated that ITGA1/ITGA2 were reproducibly found to be downregulated in prostate tumor tissues compared to normal prostate glands." (PMID 38169150, 2024). "Additional studies revealed a ligand-mediated dynamic function of ITGA2 in promoting hepatic metastasis through binding to collagen IV in liver as well as driving collagen-rich bone metastasis in a prostate tumor xenograft model." (PMID 33026975, 2020). "We next investigated the correlation between ITGA1/ITGA2 and YAP1 expression in the human prostate tumors and observed significant positive correlation in multiple independent PCa cohorts." (PMID 38169150, 2024).
asthma (2 papers, 2015 to 2019). "The authors demonstrated that the skipped isoforms of ITGA2 presented increased polyribosome binding in severe asthma." (PMID 31236190, 2019).
brain tumors (2 papers, 2019 to 2021). "Among all subtypes of brain tumors, the clinical data-mining analysis also indicated that ITGA2 and ITGB1 expression levels were significantly higher in GBM than other subtypes of brain tumors." (PMID 34120610, 2021). "To date, the role of ITGA2 and its heterodimer α2β1 in malignant brain tumors is still not well understood." (PMID 30996239, 2019). "We also demonstrated that these ITGA2 antibody-directed liposomes can effectively breach the blood-brain tumor barrier (BBTB) in vitro via GBM-induced angiogenesis effects." (PMID 30996239, 2019).
cervical squamous cell carcinoma (2 papers, 2022 to 2024). A squamous cell carcinoma arising from the cervical epithelium. "Overall, we discovered a novel regulatory pathway, MUC1/ERK/ITGA2/3, in cervical squamous cell carcinoma that may serve as a potential biomarker and therapeutic target in the future." (PMID 38702644, 2024). "MUC1 regulates ERK phosphorylation, and subsequently upregulates ITGA2 and ITGA3 expression to promote tumorigenesis in cervical squamous cell carcinoma." (PMID 38702644, 2024). "Collectively, these data demonstrated that the ITGA family of ITGA2 and ITGA3 are novel oncogenes in CSCC and may be new therapeutic targets for cervical squamous cell carcinoma." (PMID 38702644, 2024). "In addition, ITGA2 has also been demonstrated to promote PDAC progression via the focal adhesion pathway, and LAMB3 is also identified as an oncogene related to the focal adhesion pathway in cervical squamous cell carcinoma." (PMID 36612197, 2022).
Cirrhosis (2 papers, 2016 to 2025). A chronic disorder of the liver in which liver tissue becomes scarred and is partially replaced by regenerative nodules and fibrotic tissue resulting in loss of liver function. "Our analysis on cDNA microarray data derived from 228 patients with HBV-related HCC demonstrated a stepwise increase in ITGA2 expression from non-neoplastic lesions (i.e. chronic hepatitis and cirrhosis) to early HCC and from early to late HCC." (PMID 27765911, 2016).
coronary atherosclerosis (2 papers, 2019 to 2021). Atherosclerosis of the coronary vasculature. "Several studies also revealed that the genetic polymorphism of ITGA2 was associated with vascular diseases such as coronary atherosclerosis which might cause MI." (PMID 35096998, 2021). "ITGA2, an ITGA7 homolog, was reported to be associated with coronary atherosclerosis in the Chinese Han population, drawing attention to the ITGA gene family in the cardiovascular context." (PMID 30863429, 2019).
dilated cardiomyopathy (2 papers, 2017 to 2025). Cardiomyopathy which is characterized by dilation and contractile dysfunction of the left and right ventricles. "ITGA2 is involved in pathways in cancer and dilated cardiomyopathy." (PMID 29018624, 2017).
glomerulosclerosis (2 papers, 2010 to 2019). A hardening of the kidney glomerulus caused by scarring of the blood vessels. "In parallel, the glomerulosclerosis index (range 0 to 2) increased to 0.7 in ITGA2-/- mice at 150 days compared with 0.4 in their wild-type littermates." (PMID 20860797, 2010).
oral squamous cell carcinoma (2 papers, 2020 to 2025). "TC-I 15, a small-molecule inhibitor of the ITGA2-collagen interaction, significantly sensitizes oral squamous cell carcinoma (OSCC) to cisplatin in xenograft models." (PMID 40316546, 2025). "When compared to healthy mucosa, ITGA‐2 was significantly overexpressed in oral leukoplakia (P =.002) as well as in oral squamous cell carcinoma (P =.003)." (PMID 32437034, 2020). "We were able to demonstrate that ITGA‐2 was upregulated in leukoplakia and also in oral squamous cell carcinoma." (PMID 32437034, 2020). "ITGA‐2 was expressed in oral squamous cell carcinoma as it follows: five patients showed strong expression of ITGA‐2 (50%), one patient showed moderate expression (10%), three patients showed weak expression (30%), and in one tissue sample (10%), staining of ITGA‐2 was insufficient." (PMID 32437034, 2020). "ITGA‐2 and MMP‐1 were significantly overexpressed in tissue samples of oral squamous cell carcinoma in comparison to normal mucosa (P <.01 in all experiments)." (PMID 32437034, 2020).
ovarian tumor (2 papers, 2020 to 2021). "Considering the critical role of glycosylation on multiple integrins in cancer, we examined the presence of N-glycosylation of ITGA2 in ovarian tumor tissues (n = 6) and cancer cell lines (n = 7) by peptide-N-glycosidase F (PNGaseF) treatment." (PMID 34646995, 2021).
renal cell carcinoma (2 papers, 2020 to 2021). "Recently identified renal cell carcinoma cells, E006AA and E006AA-hT, were used as control cells since they have undetectable ITGA2 expression." (PMID 32824235, 2020).
thyroid (2 papers, 2018 to 2025). "However, many other molecular profiling studies have failed to implicate the ITGA2, SYT12 and CDH3 genes in thyroid tumorigenesis." (PMID 29255621, 2018).